BCHE (butyrylcholinesterase)
Diseases named in the same sentence as BCHE in open-access papers (continued):
Sharing a sentence is not in itself a finding about the gene and the disease.
diabetes (continued). "In addition, the inhibitory potential of the extract against the key enzymes responsible for world-alarming diseases like neurodegenerative disorder (acetylcholinesterase (AChE) and butyrylcholinesterase (BChE)), diabetes (α-glucosidase and α-amylase), and skin problems (tyrosinase) were estimated." (PMID 33406643, 2021). "Similarly, the capacity for inhibition against clinically important enzymes involved in major pathologies, including neurological disorders (acetylcholinesterase, AChE; butyrylcholinesterase, BChE), skin conditions (tyrosinase), and diabetes (α-amylase), were also examined." (PMID 34483902, 2021). "Our study has several limitations, for example, larger population based studies may find statistically significant differences among the mild, moderate, and severe DKA groups and further studies are needed to know if MPV, PDW and serum BChE are related to complications of diabetes other than DKA." (PMID 28376867, 2017). "In addition, the role of BChE in lipid metabolism, obesity, and diabetes mellitus has been described; however, the exact physiological function of BChE remains unknown." (PMID 25762852, 2015). "This study investigated phenolics, especially isoflavones, and inhibitory activities against the key enzymes relevant to the control of obesity (lipase), diabetes (α-amylase, α-glucosidase and DPP-IV) and AD (AChE, BChE and BACE-1)." (PMID 36496713, 2022). "Enzymes that are drug targets for NCDs include lipase (obesity), α-amylase and α-glucosidase (diabetes), angiotensin-converting enzyme (ACE) (hypertension) as well as acetylcholinesterase (AChE), butyrylcholinesterase (BChE) and β-secretase (BACE-1) (AD)." (PMID 34451608, 2021). "Also, Also, its inhibitory effects chestnut's water extract on some key and metabolic enzymes, including AChE (IC50: 0.084 μg/mL), BChE (IC50: 0.152 μg/mL), and α‐glycosidase (IC50: 0.473 μg/mL) related to diabetes and AD are very important." (PMID 40501503, 2025). "In this study, docking of alginate, a biologically active polysaccharide, was performed to gain a theoretical understanding of its possible interactions with key therapeutic enzymes (COX-1, α-amylase, BChE, SOD1, and GPX4) related to inflammation, diabetes, neurodegeneration, and oxidative stress." (PMID 41304964, 2025). "In addition, C. maxima albedo extract exhibited wide ranges of inhibitory properties against enzymes, which are drug targets for the treatment of AD (AChE, BChE, and BACE-1), obesity (lipase), and diabetes (α-glucosidase and α-amylase)." (PMID 37241861, 2023). "Moreover, we observed reduced plasma levels of zinc-α-2-glycoprotein, butyrylcholinesterase, and increased levels of complement C2 resembling findings in metabolic syndrome, diabetes and other non-communicable diseases." (PMID 32641735, 2020).
Obesity (47 papers, 2010 to 2025). Accumulation of substantial excess body fat. "Evidence suggests that genetic deficiency in BChE results in ghrelin levels that are 50% above normal, whereas BChE-enhanced mice exhibit lower plasma ghrelin levels and resist obesity on a high-fat diet." (PMID 40724174, 2025). "There is limited information on BChE activity and its relationship to obesity and metabolic risk factors in this population." (PMID 40724174, 2025). "BChE can be considered a secondary marker for obesity-related risk factors that respond to aerobic exercise; this fact was also confirmed in this study." (PMID 39195518, 2024). "Despite the clinical importance of these discoveries, few studies have tried to establish a causal relationship between BChE and obesity." (PMID 36004682, 2023). "The sensitivity of BChE to organophosphorus poisons, therapeutic effects of BChE on drug addicts, and the susceptibility to high-fat diet-induced obesity in BChE knockout (KO) mice were reported." (PMID 34062954, 2021). "Elevated serum butyryl cholinesterase (BChE) levels have also been described in individuals with obesity and MetS and there is an association between BChE activity, lipid metabolism, and MetS in adults." (PMID 33665176, 2021). "Butyrylcholinesterase (BChE) activity and polymorphisms in its encoding gene hadpreviously been associated with metabolic traits of obesity." (PMID 28497838, 2017). "The association of BCHE gene polymorphisms with obesity and relatedparameters has been demonstrated by many studies." (PMID 28497838, 2017). "Butyrylcholinesterase (BChE) activity has been associated with obesity, lipid concentrations, and CHE2 locus phenotypes." (PMID 28658346, 2017). "The relative BMI contribution to the BChE activityappears to respond to internal metabolic factors and in homeostasis imbalancesituations, such as caused by obesity." (PMID 28497838, 2017). "This change raises the chance of the possible use of BChE inhibitors for the treatment for obesity and associated disorders." (PMID 21569551, 2011). "The aim was to compare the relative intensity (RI) and activity of BChE bands (G1, G1-ALB, G2 and G4) in obese and control individuals, and search for an association between the activity of each band with obesity and SNPs of exons 1 and 4 of the BCHE gene." (PMID 21637414, 2010). "BChE-deficient mice, although apparently healthy, develop obesity when fed a high-fat diet." (PMID 40698664, 2025). "Butyrylcholinesterase (BChE) is an enzyme associated with obesity." (PMID 39195518, 2024). "Given the fact that PSNS dysfunction is widely present and is a risk factor in various cardiovascular diseases, aging, and obesity, this drug and other BChE inhibitors may offer new opportunity to improve PSNS function in these diseases." (PMID 26537347, 2015). "The enzyme butyrylcholinesterase is synthesized and secreted into blood by the liver and has been found to be positively associated with cardiovascular disease risk factors, including serum lipids, obesity, and hypertension." (PMID 24479557, 2014). "Therefore, changes in BChE activity may be considered a factor associated with obesity, enhancing its potential as a marker for obesity assessment." (PMID 40724174, 2025). "Therefore, future longitudinal studies should focus on validating population-specific effect sizes, particularly in children, and probe the causal links between the BChE–ghrelin axis and obesity progression, its metabolic consequences, and external factors in large children’s populations." (PMID 40724174, 2025). "Therefore, the present study aims to assess BChE activity, obesity-related and lipid-related indices, and dyslipidemia in both obese and non-obese children, as well as to explore associations between these parameters and obesity among Thai children." (PMID 40724174, 2025).
Obesity (continued). "However, hypertension is usually present in polymorbid patients suffering from other pathologies such as obesity, DM or even metabolic syndrome, which are also known to influence serum BChE, making a causal relationship with hypertension difficult to establish." (PMID 40698664, 2025). "The incidence of BChE variants −116A (in a noncoding region at exon 1) and K (at exon 4) was lower in obese than in nonobese adolescents, and compared to adult donors, which may suggest that these variants may protect adolescents from obesity." (PMID 29780825, 2018). "Moreover, it would be also interesting and important to determine the factors that may cause the upregulation of BChE in obesity." (PMID 26537347, 2015). "Secondly, the Pteryxin is another natural coumarin compound which is found in Peucedanum japonicum Thunb leaves, recognized for its anti-obesity properties, and it can also play the vital role as a potent butyrylcholinesterase (BChE) inhibitor." (PMID 41337159, 2025). "This study aimed to assess BChE activity, obesity-related and lipid-related indices, and dyslipidemia in obese and non-obese children, and to investigate the associations of these parameters with obesity among Thai children." (PMID 40724174, 2025). "The current study involving Thai children suggests a significant relationship between obesity and increased BChE activity, lipid-related indices, and dyslipidemia." (PMID 40724174, 2025). "Anthropometric measurements, metabolic parameters, obesity- and lipid-related indices, and BChE activity were evaluated." (PMID 40724174, 2025). "While the BChE–ghrelin axis appears to be a complex mechanism, the interconnected roles of ghrelin and BChE in the progression of obesity still warrant further investigation, particularly in children." (PMID 40724174, 2025). "Overall, BCHE holds promise as a potential target for treating obesity, but further research is warranted." (PMID 38375199, 2024). "Upregulation of butyrylcholinesterase (BChE) in obesity and consequent ghrelin resistance has a two-pronged pathophysiologic effect." (PMID 39684795, 2024). "The role of BChE in hydrolysing the hunger hormone ghrelin connects it with obesity and appetite regulation." (PMID 36004682, 2023). "These key enzymes can control the occurrence of type II diabetes (α-amylase and α-glucosidase), obesity (lipase) and AD (acetylcholinesterase (AChE), butyrylcholinesterase (BChE) and β-secretase (BACE-1))." (PMID 35684288, 2022). "For this pharmacological validation, a panel of enzymes were chosen whereby α-amylase and α-glucosidase are used for DM type 2, AChE and BChE for AD, tyrosinase and elastase for cutaneous manifestations and pancreatic lipase for obesity." (PMID 35335362, 2022). "This brief review examines some key phenomena and considers means of modulating BChE as treatments for cocaine addiction, anxiety, aggression, and obesity." (PMID 29535625, 2018). "Considering the evidence connecting BChE with obesity, the aim of this work is to investigate the effects of an energetic restriction diet on total and relative BChE activity in relation to the CHE2 C5 phenotype in obese women from Southern Brazil." (PMID 28658346, 2017). "A BChE mutant with significantly improved catalytic activity against ghrelin should be therapeutically valuable for use as an exogenous enzyme in obesity treatment." (PMID 26922910, 2016). "It is highly desired for development of a novel, safe and effective anti-obesity drug to design a mutant of human BChE with a significantly improved catalytic activity against ghrelin." (PMID 26922910, 2016). "However, findings regarding BChE activity in humans and its relationship to obesity remain inconsistent." (PMID 40724174, 2025). "Furthermore, BChE activity shows a positive correlation with lipid levels and indices related to obesity and insulin resistance." (PMID 40724174, 2025).
Obesity (continued). "Moreover, BChE activity showed a positive correlation with obesity-related and lipid-related indices, along with several metabolic parameters (p < 0.002)." (PMID 40724174, 2025). "Since BChE interacts with lipid metabolism, changes in BChE activity may affect obesity and metabolic syndrome, which depend on lipid regulation." (PMID 40116876, 2025). "Our logistic regression analysis supported the conclusion that increased TG/HDL-C ratio, non-HDL-C/HDL-C ratio, and BChE activity are linked to a higher risk of obesity." (PMID 40724174, 2025). "Additionally, BChE activity was positively correlated with obesity-related indices, blood pressure, AST, ALT, the TyG index, TyG-related indices, and various lipid-related indices and profiles (p < 0.002), except for TC, LDL-C, and glucose." (PMID 40724174, 2025). "Three variables were significantly associated with an increased risk of obesity: the upper stratum of BChE activity (OR = 5.356, p < 0.01), the non-HDL-C/HDL-C ratio (OR = 2.185, p < 0.01), and the TG/HDL-C ratio (OR = 1.703, p < 0.01)." (PMID 40724174, 2025). "An acute aerobic 1-h training protocol at an intensity of 70% VO2 peak reduced BChE activity and fatty acids in individuals at risk for obesity and did not increase post-exercise intake." (PMID 39195518, 2024). "Furthermore, OG dogs in our study also presented higher ALP, triglycerides, albumin BChE, and lower lymphocytes (presenting a stress leukogram), thus further supporting the presence of hypercortisolism in dogs with obesity, as described in human obesity." (PMID 37505862, 2023). "Moreover, plasma and liver BChE activity are elevated in patients with obesity and diabetes and rodent models of metabolic disorders, whereas it is low in individuals suffering from malnutrition or inflammatory states." (PMID 36004682, 2023). "Moreover, alongside its involvement in AD progression, an emerging role of BChE as a prognostic marker (which determines the progress of the disease) in liver and non-liver diseases, as well as in protein-energy malnutrition and obesity, has been reported." (PMID 29535344, 2018). "Because of ghrelin’s widespread impact on important emotional and physiological phenomena, and BChE’s apparent role in regulating ghrelin’s activity, extensive further research is warranted to pursue the enzyme’s influences on food intake, obesity, anxiety, and stress." (PMID 29535625, 2018). "Bearing these facts in mind, it seemed worthwhile to determine if sustained elevation of BChE could be effective in treating obesity." (PMID 29535625, 2018). "Here we propose, for the first time, that a BChE mutant with significantly improved catalytic activity against ghrelin could be used as an exogenous enzyme to control appetite and for anti-obesity treatment." (PMID 26922910, 2016). "Thus, the rising levels of BChE in obesity may relate to the body’s adjustment of energy homeostasis by modulating the BChE–ghrelin axis." (PMID 40724174, 2025). "Additionally, changes in BChE activity may be regarded as one of the obesity-related factors for improving the potential of obesity assessment." (PMID 40724174, 2025). "Butyrylcholinesterase (BChE) is an enzyme secreted by the liver under the stimulation of free fatty acids flux originating from adipose tissue, and it is recognized as a robust marker to predict the development and prognosis of low-grade systemic inflammatory conditions, such as obesity, in humans." (PMID 36713218, 2022). "Our data offer novel insights into potential mechanisms of brain dysfunction in obesity and the BChE and γGT inhibition and NO elevation might represent a novel strategy for the treatment of obesity with dyslipidemia and BOS, also demonstrate the efficacy of HCA in weight management." (PMID 21569551, 2011).
Obesity (continued). "In the obese subgroup, BChE activity remained negatively correlated with HDL-C and positively correlated with obesity-related indices, markers of insulin resistance, liver enzymes, and some lipid-related indices (p < 0.002)." (PMID 40724174, 2025). "In the children with obesity group, ALT and BChE levels correlated with anthropometric measurements, insulin resistance, and lipid parameters, leptin, interleukin-6, CRP, and sICAM-1 while BChE levels negatively correlated with adiponectin." (PMID 33665176, 2021). "Considering that in obesity the increased lipogenesis from carbohydrates leads to hyperlipidemia and to increased BChE activity, it could also explain why the energetic restriction diet, due to the decreased availability of carbohydrates in the organism, decreased BChE activity." (PMID 28658346, 2017). "Logistic regression analysis was used when obesity was used as a dependent variable, and age, sex, the upper stratum of BChE activity, TyG index, TG/HDL-C ratio, and non-HDL-C/HDL-C ratio were taken as independent variables." (PMID 40724174, 2025). "Our results indicate that BChE activity is higher in obese children compared to their non-obese counterparts and is positively correlated with obesity and lipid-related indices." (PMID 40724174, 2025). "On that regime, all mice regained some weight, but none of the BChE-treated mice returned to obesity whereas all the control mice did so." (PMID 29535625, 2018). "In light of these data, it should not come as a surprise that obesity and T2DM have been associated with the over-expression of Ach-degrading enzymes—butyrylcholinesterase (BChE) and acetylcholinesterase (AChE)—which tone down cholinergic signaling." (PMID 28243210, 2017). "The upper stratum of BChE activity (OR = 5.356), the non-HDL-C/HDL-C ratio (OR = 2.185), and the TG/HDL-C ratio (OR = 1.703) were found to be effective in evaluating and predicting the risk of obesity, even after adjusting for potential covariates (p < 0.01)." (PMID 40724174, 2025). "However, our findings support the notion that body size phenotypes and obesity-related indices—such as BMI, BMI z-score, WC, WHtR, and ABSI—are positively correlated with BChE activity, with obese children exhibiting higher BChE activity than those of normal weight." (PMID 40724174, 2025). "Also for patients with CHE2 C5− phenotype and obesity higher BChE activity was observed compared to nonobese patients." (PMID 29780825, 2018). "In addition, the -116G > A and 1914A > G polymorphismsinfluence both BChE activity and TG levels, the -116G > A dominant effect on the BChEactivity is independent of obesity status, and the 1914A > G recessive effect on theTG levels is obesity-dependent." (PMID 28497838, 2017).